IL1B (interleukin 1 beta)
Diseases named in the same sentence as IL1B in open-access papers (continued):
Sharing a sentence is not in itself a finding about the gene and the disease.
ischemic stroke (continued). "Considering the pivotal role of microglia in neuroinflammation following ischemic stroke through the production of pro-inflammatory factors such as IL-1β, TNF-α, and IL-6,28 we assessed the expression of these pro-inflammatory factors in both MCAO and OGD/R models." (PMID 40831534, 2025). "Two pro-inflammatory cytokines, TNFα and IL1β, that are known to trigger disruption of paracellular barrier properties in primary brain endothelial cells in vitro and are upregulated after ischemic stroke, contribute to Rab7a activation in primary mouse brain endothelial cells (BECs)." (PMID 41024170, 2025). "Furthermore, edaravone dexborneol exerted neuroprotective effect by inhibiting NF-κB/NLRP3/GSDMD signaling pathway and inflammatory factors (IL-1β and IL-18) in experimental ischemic stroke." (PMID 38902691, 2024). "Furthermore, individuals receiving edaravone dexborneol injection exhibited lower expression levels of interleukin (IL)-1β, IL-6, and IL-17, along with higher levels of IL-4 and IL-10 expression during the acute phase of ischemic stroke (P < 0.05)." (PMID 38902691, 2024). "We found that PTS decreased HDAC3 expression and activity, increased Nrf1 acetylation in the cell nucleus and inhibited the interaction of Nrf1 with p65 and p65 accumulation, which reduced infarct volume and neuroinflammation (iNOS/Arg1, TNF-α and IL-1β levels) after ischaemic stroke." (PMID 39198723, 2024). "In the current study, we discovered that IPC could significantly inhibit the expression of NLRP3 inflammasome components and partially reduce the level of IL-1β and IL-18 at 6 h and 24 h following ischemic stroke, especially at the 24 h time point." (PMID 37371374, 2023). "In addition, 5-BDBD treatment significantly inhibited P2X4R expression in monocytes and microglia after ischemic stroke, while reducing neurological deficit scores, interleukin-1 beta (IL-1β) levels, and BBB permeability." (PMID 36825149, 2023). "In addition, IL-16 promotes the production of inflammatory cytokines such as TNF-α, IL-1β, and IL-6, which has key effects in immune responses after ischemic stroke." (PMID 35173738, 2022). "Our data indicated that IL-1β is involved in ischemic stroke and that exercise preconditioning could reduce its expression." (PMID 36262547, 2022). "In sum, our results showed that PD-L1 knockout in platelet reduced the release of IL-1β through regulating Caspas-3/GSDME alleviated ischemic stroke and thrombotic cerebral vascular occlusions with significantly better neurological effects and survival rates after tMCAO." (PMID 35784685, 2022). "IA MSC transplantation 1 day post ischemic stroke also reduced IL-1β 8 days post stroke." (PMID 36671605, 2022). "In ischaemic stroke, the expression of IL‐1α precedes that of IL‐1β." (PMID 34792838, 2022). "In addition, after ischemic stroke, IL-1β can activate NF-kB via the activation of TLRs, enabling NF-kB to transactivate genes connected with cytokines, chemokines, and other pro-inflammatory mediators." (PMID 35055089, 2022). "By regulating IL-1β and IL-18 secretion, they play a role in ischemic stroke." (PMID 36105479, 2022). "Similar to the result, we hypothesize that alterations of TNF-α, IL-1β, and IL-6 concentrations in CSF are more suitable to represent inflammatory response after ischemic stroke." (PMID 34257822, 2021). "TNF-α enhances the detrimental effects of IL-1β, and antagonism of IL-1β either through anti-IL-1β antibodies or administration of the IL-1Receptor antagonist (IL-1RA) has been shown to be neuroprotective and improves outcomes after ischemic stroke." (PMID 34572077, 2021). "HGF suppressed microglial activation and IL-1β expression in rats with ischemic stroke." (PMID 34421795, 2021).
ischemic stroke (continued). "IL-1β is upregulated after ischemic stroke and in subacute/chronic inflammatory conditions, IL-1β is known to be a key component of the inflammatory response in the brain that mediates neurodegenerative effects of inflammation on cognition and synaptic plasticity." (PMID 33275615, 2020). "NLRP3 inflammasomes can regulate glial and neuronal cell death in ischemic stroke via enhancing generation and secretion of the pro-inflammatory cytokines including IL-1β and IL-18 and through pleiotropic impacts of cleaved-caspase-1 in regulating neuronal cell apoptosis." (PMID 32581721, 2020). "IL-1β is expressed by astrocytes during ischemic stroke, as well as neuroinflammatory disease although the precise mechanisms of IL-1β remain unclear." (PMID 32138223, 2020). "Several studies have investigated blood IL-1β levels in ischemic stroke." (PMID 32503645, 2020). "NOX inhibitor apocynin and nicotinamide adenine dinucleotide phosphate (NADPH) could inhibit the level of NLRP3, ASC, caspase-1, IL-1β and IL-18 in the cortex, improve the neurological functions, and decrease the infarct volume in ischemic stroke mouse model." (PMID 32581721, 2020). "IL-1β might be a useful biomarker for early discovery of recurrence after the first epileptic seizure in ischemic stroke patients." (PMID 32782321, 2020). "While some report increased blood IL-1β compared to controls, other studies are in line with our findings and report no changes or even reduced blood IL-1β levels in ischemic stroke patients." (PMID 32503645, 2020). "As the first identified inflammasome in cerebral ischemic injury, NLRP1 inflammasome could activate precursor caspase-1 to produce both mature IL-1β and IL-18 to mediate neurocytes death after ischemic stroke." (PMID 31416289, 2019). "Increased generation of IL-1β in patients with ischemic stroke may induce cell apoptosis, resulting in brain tissue injury in the intracerebral ischemic penumbra area and ultimately enlarging the area of cerebral infarction." (PMID 31644666, 2019). "The pro-inflammatory cytokine IL-1β plays a crucial role in the pathogenesis of ischemic stroke." (PMID 31644666, 2019). "IL-1β has been the focus of many experimental studies of ischemic stroke." (PMID 22707991, 2012). "Whereas IL-1β is primarily neurotoxic in ischemic stroke, TNF-α may have neurotoxic and/or neuroprotective effects." (PMID 18947400, 2008). "EREG and IL1B were specifically implicated in this functional category, suggesting they may modulate key receptor-mediated signaling events pertinent to ERK pathway activation in ischemic stroke." (PMID 40636523, 2025). "Moreover, NLRP3 inflammasome activation can up-regulate the IL‐1β expression and further promote the cascade of inflammation in the central nervous system, leading to the aggravation of nerve injury in patients with ischemic stroke." (PMID 41246459, 2025). "However, the distinct roles of the two major IL-1 receptor type 1 agonists, IL-1α and IL-1β, and the specific role of IL-1α in ischemic stroke remain largely unknown." (PMID 40110693, 2025). "Additionally, in a study about the relationship between ex vivo cytokine synthesis and 3-month outcomes after ischemic stroke, decreased release of IP-10, TNFα, IL-1β, and IL-12; increased release of IL-10 and IL-8; and higher plasma IL-6 levels were associated with poor outcomes." (PMID 36439158, 2022). "In addition, IL‐1β may be a useful biomarker for early detection of relapse after the first epileptic seizure in patients with ischaemic stroke." (PMID 34792838, 2022). "In the acute phase of ischemic stroke, resident microglia and recruited macrophages assume an M2 phenotype, and the immune-mediated inflammatory response is activated, resulting in the secretion of a number of inflammatory cytokines (IL-6, IL-1β, and TNF-α and the proteolytic enzymes MMP 3 and 9)." (PMID 34276353, 2021).
ischemic stroke (continued). "However, to date, the association between IL-1β level and recurrence after the first epileptic seizure has not been analyzed in ischemic stroke patients, moreover, the value of IL-1β level applied in predicting seizure recurrence has not been evaluated." (PMID 32782321, 2020). "IL-1β may be decreased by SB for ischemic stroke in middle-aged female rats." (PMID 33537033, 2020). "Therefore, IL-1β might be a useful biomarker for early discovery of recurrence after the first epileptic seizure in ischemic stroke patients." (PMID 32782321, 2020). "Interestingly, Nec-1 treatment could simultaneously inhibit the formation of mature IL-1β in the brain following ischemic stroke." (PMID 31440386, 2019). "Therefore, lowering the cytotoxic effects of TNF-toxic and IL-1β in the CNS by ANGPTL2 suppression may serve as an attractive therapeutic option in the acute phase of ischemic stroke." (PMID 27861531, 2016). "For example, in a mouse model of ischemic stroke, microglia‐specific PGC‐1α overexpression suppresses NLRP3 inflammasome activation; reduces TNF‐α, IL‐1β, and IL‐6 production; enhances mitophagy; and significantly improves neurological outcomes." (PMID 41517974, 2026). "For example, reversing dysbiosis through the ingestion notoginseng saponins restored BBB integrity via increased occludin and Zo1 expression, and reduced proinflammatory cytokine expression (IL-1B, IL-6, TNF) in a rodent model of ischemic stroke." (PMID 40485663, 2025). "In ischemic stroke models, butyrate produced by C. butyricum inhibits excessive microglial activation via Akt phosphorylation, downregulates hippocampal TNF-α/IL-1β levels, and reduces infarct volume." (PMID 40895486, 2025). "Based on this, the present study investigated the effects of 25 μg estrogen (E) and 10 mg progesterone (P) per kg body weight on the inflammatory factors IL-1β and CD4+ and the infarct volume in a rat model of ischemic stroke." (PMID 40809171, 2025). "In ischemic stroke, microglia polarize into distinct phenotypes: pro-inflammatory M1 (secreting TNF-α, IL-1β, IL-6) and pro-angiogenic M2 (releasing IL-10, TGF-β, VEGF)." (PMID 40988927, 2025). "During ischemic stroke, microglia produce pro-inflammatory cytokines such as tumor necrosis factor (TNF), interleukin 1 beta (IL1β), interleukin 6 (IL6), and proteolytic enzymes such as matrix metalloproteinase 9 (MMP9)." (PMID 40676515, 2025). "Using this approach, we identified a distinct gene signature—termed GSERK—including GADD45A, DUSP1, EREG, IL1B, JUN, and GADD45B as central regulatory nodes within ischemic stroke-related co-expression networks." (PMID 40636523, 2025). "Silencing HDAC9 has been shown to reduce infarct size, suppress pro-inflammatory cytokine expression (e.g., IL-1β, TNF-α, IL-6), and improve neurological function, underscoring its potential as a therapeutic target in ischemic stroke." (PMID 40867911, 2025). "Cytokines play a pivotal role in the inflammatory response following an ischemic stroke with TNF-α, IL-1β, IL-6, and IL-10 being particularly significant." (PMID 40095189, 2025). "Beyond IL-1β and TNF-α, numerous other cytokines play significant roles in the pathological progression of ischemic stroke." (PMID 41451205, 2025). "Clinical studies have associated oxidative stress and pro-inflammatory cytokines such as IL-1β, IL-6, and TNF-α with poor outcomes in ischemic stroke patients." (PMID 39596503, 2024). "Ischemic stroke increases the release of TNF-α and IL-1β, which influence the severity of neurological deficits and cell damage through the production of free radicals." (PMID 38527023, 2024). "As the results showed, there was increased production of pro-inflammatory cytokines, including TNF-α, IL-6, and IL-1β, in the CMI+PT group compared to the PT group on the first day after ischemic stroke." (PMID 38216560, 2024).
ischemic stroke (continued). "IL-1β and IL-18 antagonists have been shown to inhibit the NLRP3 inflammasome consequently attenuating the adverse effects of ischemic stroke." (PMID 41542272, 2024). "Ischemic stroke induces activation of NF-κB, overproduction of inflammatory factors such as TNF-α and IL-1β, activation of caspase proteins, and induction of neuronal cell death." (PMID 38527023, 2024). "Pro-inflammatory cytokines, including IL1α, IL1β, IL6, TNFα, and the number of CD16 + and CD206 + microglia (especial CD16 + microglia), increased after ischemic stroke." (PMID 38287382, 2024). "During ischemic stroke, astrocytes become reactive and produce several proinflammatory cytokines, such as TNF-α, IL-1β, IL-6, and IFN-γ, in response to ischemia." (PMID 39707228, 2024). "In ischemic stroke models, bile acid-induced TGR5 activation reduces the expression of NLRP3 inflammasomes and IL-1β, offering therapeutic benefits." (PMID 39328272, 2024). "We observed that PTS protected against neuronal damage and suppressed ischaemic stroke-induced changes in the levels of TNF-α, IL-1β and iNOS." (PMID 39198723, 2024). "Following ischemic stroke, MCP-1−/− mice exhibit reduced expression of IL-1β, IL-6, and G-CSF, which helps prevent further damage to the blood–brain barrier in mice." (PMID 39649720, 2024). "In the cellular model of ischemic stroke, the expression levels of lncRNA AC136007.2 were decreased along with decreased cellular viability, induced apoptosis, and increased secretion of IL-1β, IL-6, and TNF-α." (PMID 39021183, 2024). "Cyclooxygenase inhibition can eliminate TNF-α-, IL-1β-, and IL-6-induced increase in endothelial paracellular permeability, suggesting a role for arachidonic acid in increasing BBB permeability during ischemic stroke." (PMID 37840921, 2023). "In the early phase of experimental ischemic stroke, microglia produce pro-inflammatory mediators such as TNF-α, IL-1β and reactive oxygen species resulting in further damage and secondary cell death in the penumbra region." (PMID 37193998, 2023). "In ischemic stroke, MMP‐9 activates proinflammatory cytokines and chemokines, such as CXCL8, IL‐1β, and TNF‐α." (PMID 37452512, 2023). "The elevation of p-Akt/p-mTOR and the reduction of IL-1β, TLR4, p-38, and p-p38 levels have also been observed after curcumin administration in ischemic stroke and were concomitant with curtailed LC-3-II and NLRP3 markers." (PMID 37915409, 2023). "These authors noted decreased levels of interleukin-1 (IL-1b) and matrix metallopeptidase 9 (MMP 9) in the periinfarct area of mice suffering from ischemic stroke." (PMID 37388676, 2023). "To further investigate the relationship between NLRP1 and inflammatory factors in ischemic stroke patients, we measured the serum levels of NLRP1, CRP, IL-6, TNF-α, and IL-1β by ELISA." (PMID 37000063, 2023). "Chronic elevation of IL1β suppresses BDNF and is a potential therapeutic target in the treatment and recovery from ischaemic stroke." (PMID 35639336, 2023). "In the present study, our findings revealed that IFNβ attenuated tPA-upregulated inflammatory molecules, CD86, IL-1α, and IL-1β, and promoted anti-inflammatory molecules, Arg1 and CD206, in MG during the acute phase of ischemic stroke." (PMID 37063896, 2023). "Some researchers have shown that PEMF significantly decreased inflammatory IL-1β and MMP-9 in the ischemic stroke brain." (PMID 35163096, 2022). "Ischemic stroke is accompanied by the production and release of proinflammatory cytokines (mainly TNF-α and IL-1β), as previously demonstrated." (PMID 36105479, 2022). "In this study, we demonstrated that the ischemic stroke-induced activation of NLRP3 was significantly reduced by MFSCE, as so were the downstream targets of cleaved caspase-1 and caspase-11, mature IL-1β, and IL-18." (PMID 35454994, 2022). "The expression of pro-inflammatory cytokines (IL-1β, IL-6, IL-8, TNF-α) in the cortex of ischemic stroke mice was detected after the occurrence of cerebral ischemia." (PMID 35173738, 2022).
ischemic stroke (continued). "Consistent with the network pharmacology findings, in the current study, it is revealed that IL-1β, TNF-α, IL-6, and IL-4 were significantly increased in the cerebral cortex and hippocampus after ischemic stroke." (PMID 36338345, 2022). "Inflammatory cytokines including IL-1β, IL-8, and hs-CRP were considered to predict recurrent ischemic stroke independently." (PMID 36278219, 2022). "Previous reports showed that JQ1-treated animals exhibit a marked reduction in the expression of pro-inflammatory mediators IL-1β, IL-6, IL-17, IL-18, and TNF-α in the brain in rodent ischemic stroke models." (PMID 35761277, 2022). "Moderate hypothermia reduces the inflammatory response Interleukin 1 beta (IL-1β) and Tumor Necrosis Factors alpha (TNF-α), oxidative stress, and energy consumption after an ischemic stroke." (PMID 36569944, 2022). "Microglia release proinflammatory cytokines such as IL-1β, IL-6, and TNF-α in the acute phase of ischemic stroke, impeding postinjury neural regeneration and producing poorer long-term neurological outcomes." (PMID 36338577, 2022). "In RT-PCR assays, mRNA levels of TNF-α, IL-1β, MMP-2, and MMP-9 were remarkably elevated following ischemic stroke." (PMID 36186136, 2022). "Earlier studies have shown that after ischemic stroke, Zileuton suppresses NF-κB activation and the levels of inflammatory cytokines were decreased (LTB4, TNF-α, IL-6, IL-1β)." (PMID 33878031, 2021). "Here, we sought to examine the concentrations of inflammatory cytokines (IL-1β, IL-6, and IL-10) and growth factors (VEGF, BDNF/TrkB and TGF-β) 24-h and 30 days after ischemic stroke." (PMID 34408211, 2021). "SYK inhibitor R406 significantly deactivated NLRP3, Caspase-1, and GSDMD-N signaling; reduced the concentration of IL-1β; and attenuated GSDMD-N induced membrane pores in mice with ischemic stroke." (PMID 33402173, 2021). "In ischemic stroke, manifestation of downregulated NF-κB was supplemented by the knockdown of TNF-α, IL-6 and IL-1β." (PMID 33658008, 2021). "Immediately after ischemic stroke, A1 astrocytes produce and secrete several proinflammatory mediators, such as IL-6, TNF-α, IL-1α, IL-1β, and IFN-γ." (PMID 34211624, 2021). "In different types of models, such as ischemic stroke, GPER1 on microglia was also suggested to mediate the effect of decreasing IL-1β and TNF-α under G1 or estradiol stimulation." (PMID 34239558, 2021). "The activated microglia subsequently release chemokines, cytotoxic mediators, and cytokines, including IL-1β, TNF-α and IL-6, triggering the inflammatory cascade after an ischemic stroke, thus further exacerbating neuroinflammatory damage." (PMID 32419986, 2020). "Other researches prove that proinflammatory cytokines such as IL-1b, IL-6, and TNF-a are released by microglia and upregulate after ischemic stroke." (PMID 32382569, 2020). "In an ischemic stroke mouse model, ORM inhibited the production of the inflammatory cytokines IL-1β, IL-6, and TNF-α." (PMID 33013889, 2020). "The results support findings from animal studies that IL-1α, IL-1β, IL-1Ra, and TNF are produced by subsets of primarily microglia and leukocytes in ischemic stroke tissue." (PMID 32503645, 2020). "Gm4419 promoted neuroinflammation by inducing IκB phosphorylation and NF-κB signaling activation after ischemic stroke, and the levels of tumor necrosis factor-α (TNF-α), interleukin-1β (IL-1β) and IL-6 were increased." (PMID 33613191, 2020). "Besides, light-emitting diode (LED) treatment could decrease neuroinflammatory reactions and brain damage after ischemic stroke via reducing cell death, decreasing IL-1β and IL-18, and inhibiting NLRP3 inflammasome, MAPK signaling, TLR-2 levels and NF-κB activation." (PMID 32581721, 2020). "Accordingly, ischemic stroke was found to significantly increase the levels of cleaved caspase-1, ASC, NLRP3, cleaved GSDMD, IL-1β, and IL-18." (PMID 33584203, 2020).